PPARA (peroxisome proliferator activated receptor alpha)
Diseases named in the same sentence as PPARA in open-access papers (continued):
Sharing a sentence is not in itself a finding about the gene and the disease.
colitis (continued). "More recently, we have verified that mice with DSS induced experimental colitis are characterized with both promoted metabolic excretion and increased de-novo hepatic synthesis of BAs, initiated by the activated intestinal PPARα-UGTs and compromised FXR-FGF15 signaling." (PMID 28969019, 2017). "Thus, activation of PPARα appears to be a target for controling colitis including in this inoculated Il10−/− mouse model." (PMID 20671959, 2010). "PPARα might be one of the key mediators in these signaling processes before and after colitis onset in Il10−/− mice." (PMID 20671959, 2010). "Gene expression changes in 12-week-old Il10−/− mice were related to PPARα signaling likely to control colitis, but how PPARα activation might regulate intestinal IL10 production remains to be determined." (PMID 20671959, 2010). "Furthermore,we demonstrated ligands for PPARγ and PPARα inhibit colitis-related coloncarcinogenesis usingour AOM/DSS mouse model." (PMID 18483618, 2008). "In addition to its alreadymentioned anti-inflammatory effects, PPARα protects the intestine from colitis-inducedpermeability." (PMID 19125181, 2008). "It has also been proposed that PPARα participates in the intestinal epithelial barrier system, where the absence of its function may enhance ileum permeability during experimental colitis, while endogenous PPARα ligands can reverse this situation through the regulation of apoptosis." (PMID 32536865, 2020). "Studies have shown that intestinal barrier damage in IBD patients and mice with colitis is related to the activation of FXR and PPARα by dysregulation of bile acid metabolism." (PMID 40004195, 2025). "In rats with colitis, despite the rats receiving the symbiotic having higher rates of CB2, MOR and PPARα mRNA than the untreated animals, only the CB1 mRNA levels increased significantly (78.6 ± 12.7 vs. 19.7 ± 4.5, +398%; p < 0.05)." (PMID 39409061, 2024). "Predictions were validated using a balanced and potent PPARα/γ-dual-agonist (PAR5359) in Citrobacter rodentium- and DSS-induced murine colitis models." (PMID 35288651, 2022). "In the animal IBD model, the double PPARα/γ agonist PAR5359 significantly alleviated both Citrobacter rodentii- and DSS-induced colitis." (PMID 36430628, 2022). "DSS-induced colitis mice showed significantly decreased expressions of PPARα, PGC-1α, and thermogenic genes including ND5, Prdm16, Cidea, Elovl3, Dio2, and UCP1 both in SAT and BAT compared to non-colitis control mice." (PMID 33674694, 2021). "One study showed how the PPARα-UGT pathway increased de novo bile acid synthesis, exacerbating mouse model colitis." (PMID 35003101, 2021). "Gene expression analysis indicated a decrease of PPARα, PPARγ and NAAA, and an increase of FAAH and iNOS in the active colitis mucosa." (PMID 22662201, 2012). "In PPARα-KO and WT mice, verbascoside ameliorated DNBS-induced colitis in a PPARα-mediated manner." (PMID 39451206, 2024). "The absence of PPARα and subsequent dysbiosis facilitated the development of colitis in mouse model, due to up-regulation of the Th1/Th17 response." (PMID 36430628, 2022). "Endocannabinoid NAEs derivatives with PPARα activity, such as oleoylethanolamide (OEA) and palmitoylethanolamide (PEA), also have anti-inflammatory properties, with evidence that they can protect against colonic inflammation." (PMID 32536865, 2020). "Based on these studies, the second hypothesis was that PPARα and IL10 signaling pathways are interlinked during colitis." (PMID 20671959, 2010). "For example, a recent study reported that induction of PPARα is lacking in the liver of CF mice compared to wild type animals following colitis induced bile duct injury." (PMID 16875506, 2006). "The anti-inflammatory effect of fenofibrate by delaying colitis onset and progression in Il10−/− mice indicates that IL10 is not required in PPARα signaling." (PMID 20671959, 2010).
colon carcinoma (57 papers, 2005 to 2025). "Additionally, it has been shown that in a mouse colon cancer model, PPARα-deficient mice exhibit reduced tumor growth rates compared to wild-type mice." (PMID 39875357, 2025). "The bulk of both “in vivo” and “in vitro” results strongly suggests that colon cancer cells are characterized by decreased susceptibility to apoptosis deriving from decreased arachidonic acid content, PPARα and proapoptotic proteins, and increased antiapoptotic proteins and COX-2." (PMID 19841681, 2009). "In PPARα-deficient murine colon cancer models, increased levels of DNMT1 and PRMT6 promote colon carcinogenesis by mediating methylation of p21 and p27, respectively; the PPAR agonist fenofibrate suppresses AOM/DSS-induced colorectal carcinogenesis." (PMID 40718481, 2025). "Studies have demonstrated that PPARδ can promote colon cancer proliferation and migration, whereas PPARα and PPARγ retard colon cancer progression." (PMID 40675969, 2025). "Acid-adapted colon cancer cells have been observed to reorganize cancer cell metabolism by increasing PPARα activity and participate to some extent in cancer cell proliferation and invasion." (PMID 39875357, 2025). "Early experiments have indicated that the activation of PPARα plays a role in the apoptotic process in colon cancer." (PMID 39875357, 2025). "On the other hand, PPARα activation showed inhibitory effects on the proliferation of gliomas and ovarian, lung, and colon cancer cells." (PMID 38097734, 2024). "Previous findings demonstrated that a PPARα activator suppressed the development of colon cancer by up-regulating the expression of p21 and p27, suggesting a PPAR strategy for the prevention of colon cancer." (PMID 37305395, 2023). "Regarding colon cancer and ampullary cancer, the expression of PPARα was higher in cancer tissues than in their normal counterparts, which is inconsistent with the present pattern, whereas its expression was lower in mouse lung cancer." (PMID 37305395, 2023). "Recently, WY-14,643 has been proven to suppress tumorigenesis in colon cancer and lung cancer in vivo in a PPARα-dependent manner." (PMID 36384580, 2022). "Here, using bioinformatics analysis, we found that PPARA was expressed at relatively low levels in pancancers, and Kaplan-Meier analyses revealed that high PPARA protein expression was correlated with better survival of patients with colon cancer." (PMID 33959155, 2021). "In the present study, we analyzed the expression levels of PPARs in pancancers and noted that PPARA was expressed at low levels in several types of tumors, including colon cancer." (PMID 33959155, 2021). "In conclusion, the present work illustrated that activation of PPARA by fenofibrate administration protected against colon cancer progression through epigenetic modifications." (PMID 33959155, 2021). "In colon cancer, intestinal PPARα protects against colon carcinogenesis via regulation of methyltransferases DNMT1 and PRMT642." (PMID 33414412, 2021). "Colon cancer samples with high PPARA protein expression were observed to have a better prognosis than those with low PPARA levels." (PMID 33959155, 2021). "Previous report shows that PPARα enhances the colon cancer cell sensitivity in response to hydroxycamptothecin (HCPT), while the mechanism is still unclear." (PMID 26556865, 2015). "15d-PGJ2 and troglitazone suppress DNA synthesis and induce apoptosis in a dose-dependentway in HT-29 colon cancer cells, whereas ligands for PPARα and β/δ had nosignificant effect." (PMID 18615196, 2008). "“In vivo” PPARγ and PPARα proteins content wasevaluated in cancer specimens from patients undergoing surgery toremove colon tumors." (PMID 17389773, 2007). "Determination of PPARα “in vivo” inspecimens of colon cancer showed it to be decreased in comparison withmucosa specimens, alongside an increase in the antiapoptotic proteins Bcl-2and Bcl-XL." (PMID 17389773, 2007).
colon carcinoma (continued). "PPAR activity is also closely linked to the eicosanoid pathway of inflammation and PPARα induces cyclo-oxygenase-2 (PTGS2) expression, which is linked to the development of colon cancer." (PMID 16569247, 2006). "PPARα has been shown to be expressed in colon tumours and overexpressed in breast and prostate tumours." (PMID 15583697, 2005). "Fibrate drugs, which belong to the class of PPARα agonists, can inhibit triglyceride synthesis by promoting β-oxidation, thereby modulating widely altered lipid signaling in cancer cells and impacting colon cancer survival and proliferation." (PMID 39875357, 2025). "We further confirmed that PHA665752 and NSC3852 induce cell killing depending on the level of PPARα expression, and as such, their potency for killing the SW620 colon cancer cell line that expresses the lowest level of PPARα was less potent than for the KAIMRC1 and MDA-MB-231 cell lines." (PMID 39859448, 2025). "The loss of PPARα in the intestines has been proposed to increase DNMT1 (methyltransferase 1)-mediated p21 methylation and PRMT6 (protein arginine methyltransferase 6)-mediated p27 methylation, thereby promoting the development of colon cancer." (PMID 37305395, 2023). "Interestingly, PPARα acts as a suppressor of colon carcinogenesis in mice and is downregulated in mouse colonic tumours." (PMID 34638914, 2021). "Moreover, activation of PPARα by fenofibrate protected human PPARα transgenic mice from chemical-induced colon cancer." (PMID 34572440, 2021). "PPARA was downregulated in colon cancer and correlated with TNM stage in the TCGA COAD dataset." (PMID 33959155, 2021). "In addition, colon cancer cell lines with high endogenous expression of methyltransferases and low endogenous expression of PPARA relative to normal NCM460 and HIEC cells were selected for further in vitro assays." (PMID 33959155, 2021). "PPARα expression inhibition in a hydroxicamptothecin resistant colon cancer cell line." (PMID 34638914, 2021). "The PPARA agonist, fenofibrate, might serve as an applicable agent for epigenetic therapy of colon cancer patients." (PMID 33959155, 2021). "Interestingly, miR-506, which is frequently dysregulated in cancer, has been shown to inhibit PPARα expression in the hydroxicamptothecin-resistant colon cancer cell line SW1116." (PMID 34638914, 2021). "Finally, PPARα was reported to be also a target of miR-506, which is increased in human colon cancers and contribute to chemotherapy resistance by down-regulating PPARα expression." (PMID 23024649, 2012). "Moreover, the importance of PPARα in apoptosis has also been seen by other “in vitro” studies, stimulating interest in the investigation of PPARα as a possible therapeutic target to prevent colon cancer formation." (PMID 19841681, 2009). "Moreover, the results obtained on treating cell lines with PPAR ligands confirm observations in colon cancer: there is an inverse correlation between PPARα and Bcl-2 and between PPARγ and c-Myc." (PMID 17389773, 2007). "Drugs that activate PPARα may be used in the prevention or treatment of colon cancer." (PMID 35743814, 2022). "Members of the peroxisome proliferator-activated receptor (PPAR) family of nuclear receptors (i.e., PPARγ, PPARα, and PPARβ/δ) have been identified as activators of Angptl4 expression in adipose tissue, liver, skeletal and cardiac muscle, myofibroblasts, and colon carcinoma cells." (PMID 22479192, 2012). "In fact, the low level of arachidonic acid was accompanied by an increase in antiapoptotic protein Bcl-2 and by the reduction of proapototic proteins and PPARα, indicating a decreased susceptibility to apoptosis in colon cancer with respect to non-neoplastic mucosa." (PMID 19841681, 2009).
colon carcinoma (continued). "Besides interactions of PPARα and TET enzymes in early development, associations of PPARα inhibition with the increased expression of DNA methyltransferase I (DNMT1) and protein arginine methyltransferase 6 (PRMT6) have already been demonstrated in colon cancer and the liver." (PMID 36551797, 2022). "Expression of PPARA in TGBC-18 TKB ampullary cancer cells was higher in gastric cancer cells (AGS and MKN45) and colon cancer cells (HCT116) by semiquantitative RT-PCR." (PMID 33390794, 2021). "In colon cancer, the absence of PPARα and PPARβ/δ expression promotes cancer growth, and PPARγ suppresses tumorigenesis through the regulation of and interaction with β-catenin." (PMID 36221049, 2022). "Peroxisome proliferator activated receptor alpha (PPARα), a nuclear receptor that regulates lipid homeostasis, inhibits DNA methyltransferase 1 (DNMT1)-mediated cyclin dependent kinase inhibitor 1A (CDKN1A) and PRMT6-mediated cyclin dependent kinase inhibitor 1b (CDKN1B) to promote colon cancer." (PMID 35004688, 2021).
colorectal cancer (55 papers, 2010 to 2026). A primary or metastatic malignant neoplasm that affects the colon or rectum. "In a small-scale cross sectional study (n = 100 patients), the overexpression of PPARα in the tumor microenvironment (TME) of colorectal cancer has been linked to poorer prognosis." (PMID 33946986, 2021). "Previous studies showed that activation of PPARα by exogenous agonists causes inhibition of tumor cell growth in cell lines derived from colorectal cancer." (PMID 23024650, 2012). "PPARα activation is commonly implicated in hepatocarcinogenesis protocols for rodents in which its anti-apoptotic action is assumed to play a crucial role; however, activation of PPARα by exogenous agonists reduces tumor cell growth in cell lines derived from colorectal cancer." (PMID 27482818, 2016). "According to The Human Protein Atlas database, the colorectal cancer cell line SW620 exhibits the lowest PPARα expression." (PMID 39859448, 2025). "Another study demonstrated that the overexpression of miR-506 in an HCPT-resistant colorectal carcinoma cell line contributed to the resistance against HCPT by suppressing PPARα expression." (PMID 38372868, 2024). "In a DSS-induced mouse model of innate immune-mediated colitis, Wy-14643-activated PPARα inhibited colorectal cancer by reducing inflammatory factor levels." (PMID 37251321, 2023). "We investigated the effect of the PPARα activators fenofibrate and WY-14643 and the PPARα inhibitor GW6471 on the levels of activated p38 (p-p38) in the colorectal cancer cell lines HT-29 and Caco2 in relation to their differentiation status." (PMID 37175404, 2023). "Activation of PPARα by fenofibrate protects human PPARα transgenic mice from chemically induced colorectal cancer." (PMID 37175404, 2023). "We investigated the effect of the PPARα activators fenofibrate and WY-14643 and the PPARα inhibitor GW6471 on the levels of activated p38 (p-p38) in the colorectal cancer cell lines HT-29 and Caco2 cells in relation to their differentiation status." (PMID 37175404, 2023). "Recently, a study showed that PPAR expressions are explicitly deregulated in colorectal cancer (CRC), with PPARα and PPARδ being overexpressed, while PPARγ is suppressed in CRC tumor tissues." (PMID 35481240, 2022). "To elucidate the relationship between PPARα and protein/lipid messenger in intestinal cell differentiation, we detected antigens of interest in poorly differentiated colorectal carcinomas and adjacent normal tissues." (PMID 36101378, 2022). "PPARα signaling also ensures a high lipid turnover rate, sustaining the high energy demand to maintain stemness and self-renewal in pancreatic and colorectal cancer stem cells." (PMID 33946986, 2021). "We investigated the role of PPARα in the differentiation of intestinal cells using HT-29 and Caco2 cell lines as a model as well as human normal colon and colorectal carcinoma tissues." (PMID 34572440, 2021). "The aim of this study was to investigate the possible role of PPARα in intestinal cell differentiation using in vitro differentiated HT-29 and Caco2 cells and tissue samples of normal epithelium as well as colorectal carcinoma." (PMID 34572440, 2021). "Some studies have shown that in colorectal cancer, PPARα activated by fenofibrate can stall the progress of colorectal cancer by inhibiting the expression of proinflammatory factors and by increasing the antioxidant capacity of cells." (PMID 33029112, 2020). "For colorectal cancer, PPARα activated by Wy-14643, a potent exogenous PPARα ligand, inhibits inflammation by reducing the levels of inflammatory factors to inhibit colorectal cancer." (PMID 31336903, 2019). "Even so, PPARα stimulation in human colorectal cancer lines is moderately pro-inflammatory and stimulates prostaglandin H synthase-2 expression." (PMID 27927180, 2016). "Although the procarcinogenic effects of PPARα in rodent hepatocarcinoma are evident, less is known about the role of PPARα in human colorectal cancer." (PMID 23024650, 2012).
colorectal cancer (continued). "PPARα (mRNA and protein) expression levels were decreased in colorectal cancer in the APCMin /+ mouse model of familial adenomatous polyposis compared with matched non-malignant tissue." (PMID 20671959, 2010). "In addition, the immunohistochemical profiles of PIP5K1C, PIP2, PI3K, and PTEN in poorly differentiated colorectal carcinomas and adjacent normal colon tissue were examined and compared with PPARα levels." (PMID 36101378, 2022). "PPARA was in the gene panel of ColoPrint with overexpression; nevertheless neither this article nor any other article has shown how this gene is involved in the development of colorectal cancer." (PMID 33968339, 2021). "Based on GRN results, the functional relationship between two genes pairs ({IL2R, CYFIP2} and {FOXM1, PPARA}) in colorectal cancer was found to be statistically significant by the differential co-expression method; this result was also confirmed by GRN and GSEA methods." (PMID 33968339, 2021). "Moreover, we found similar levels of PPARα expression in colorectal carcinomas in comparison to adjacent normal epithelium." (PMID 34572440, 2021). "In addition, we found similar levels of PPARα expression in colorectal carcinomas in comparison to adjacent normal epithelium." (PMID 34572440, 2021). "PPARα agonists suppress human colorectal carcinoma cell growth." (PMID 27835866, 2016). "PPARα signaling also improves lipid turnover, which is the rate at which lipids are removed and stored in fat cells, and maintains the high energy requirements of tumor cells to ensure the stemness and self-renewal ability of pancreatic and colorectal cancer stem cells." (PMID 37251321, 2023). "Moreover, as carcinogenesis could be seen as result of the disruption of the normal differentiation process, the PPARα expression pattern in colorectal carcinoma and healthy margin tissues samples was also explored." (PMID 34572440, 2021). "In colorectal cancer cells, APN promotes cell survival during glucose deprivation by AMPKα and PPARα activation and IGF-1/PI3k/Akt/mTOR pathway inhibition." (PMID 23894332, 2013). "For colorectal cancer SW480 cells, clofibrate significantly inhibits tumor proliferation and sensitizes SW480 cells to chemotherapy drugs in a PPARα-dependent manner, thereby inducing anti-apoptotic Bcl2 protein degradation and promoting autophagy in tumor cells." (PMID 37251321, 2023). "It was an unexpected finding because in vitro experiments with the PPARα activators and inhibitor in colorectal carcinoma cells showed relationship in expression of PPARα with PIP5K1C and PTEN enzymes but not with PI3K." (PMID 36101378, 2022). "Unlike PPARα and γ, which present both pro-tumor and anti-tumor effects in colorectal cancer, different experimental evidences showed the pro-tumorigenic role of PPARβ/δ, mainly through its involvement in the APC/β-catenin/K-Ras oncogenic pathway." (PMID 29966227, 2018).